EYA4 (EYA transcriptional coactivator and phosphatase 4)
Diseases named in the same sentence as EYA4 in open-access papers (continued):
Sharing a sentence is not in itself a finding about the gene and the disease.
tumor (22 papers, 2009 to 2025). "In the TAM cohort, loss of methylation at cg04334496 in NR was associated with an increase in EYA4 expression, which has tumor-promoting functions and acts as a transcriptional activator and phosphatase." (PMID 40705465, 2025). "EYA4 has been associated with several human cancers, with tumor-suppressing and tumor-promoting roles." (PMID 37292941, 2023). "Despite extensive researches on identification of EYA4 as a tumor suppressor, the mechanism underlying its deficiency in PDAC remains poorly understood." (PMID 36741265, 2023). "The anti-neoplastic role of EYA4 recently gains considerable interest since epigenetic silencing of eya4 gene has been found to be associated with oncogenic signal amplification, tumor aggressiveness and unfavorable prognosis 3, 30-32." (PMID 36741265, 2023). "Although EYA4 was found to be involved in the regulation of tumour progression in HCC, the underlying molecular mechanism remains poorly understood." (PMID 30957411, 2019). "The aim of this study was to elucidate the potential tumor-suppressive role of EYA4 in HCC and its underlying mechanism." (PMID 29764501, 2018). "EYA4 functions as a tumor suppressor in pancreatic ductal adenocarcinoma (PDAC) by inhibiting the activation of β-catenin and ID2, representing a favorable prognostic factor in PDAC." (PMID 36750914, 2023). "We characterize the inhibitory role of TRIM69 in the EYA4-driven tumor suppression through genetic and biochemical approaches as well as in vitro and in vivo studies." (PMID 36741265, 2023). "Downregulation of EYA4 expression in cells of epithelial origin is consisting with its tumor suppressor function in these entities." (PMID 32603365, 2020). "The univariate analysis indicated that HBs and HBe antigens, tumour size, tumour number, microvascular invasion and EYA4 expression remarkably correlated with RFS." (PMID 30957411, 2019). "Together, we provide proof that EYA4 is a novel tumour suppressor in HCC and a new prognostic biomarker and therapeutic target in HCC." (PMID 30957411, 2019). "Suppression of tumour progression through EYA4 overexpression holds promise as a method for HCC treatment." (PMID 30957411, 2019). "In the analysis of 302 HCC specimens, we revealed that decreased expression of EYA4 correlated with tumour differentiation status." (PMID 30957411, 2019). "Herein, we report that low expression of EYA4 is closely related to tumour differentiation status and poor prognosis of HCC." (PMID 30957411, 2019). "EYA4 appears to have both tumor-promoting and tumor-suppressing functions in different cellular contexts." (PMID 29764501, 2018). "Collectively, these data suggested that EYA4 functions as a bona fide tumor suppressor in human HCC cell lines because the overexpression of EYA4 abrogates tumor malignancy." (PMID 29764501, 2018). "The current work aimed to explore the mechanisms through which EYA4 functions as a tumor suppressor in HCC." (PMID 29764501, 2018). "We assessed the effects of EYA4 on cell growth, invasion and tumor formation as well as RAS-related protein 1 (RAP1) expression in HCC." (PMID 29764501, 2018). "Our findings provide a functional and mechanistic basis for identifying EYA4 as a bona fide tumor suppressor that disrupts aberrant activation of the NF-κB/RAP1 signaling pathway and thus orchestrates a physiological impediment to HCC growth and invasion." (PMID 29764501, 2018). "Cells expressing EYA4 S37E had intact nuclear accumulation of β-catenin and Id2 transcription upon Wnt-3a stimuli, suggesting that Ser37 autophosphorylation restrains the tumor-suppressive phenotypes of EYA4." (PMID 36741265, 2023). "Since TRIM69 elicits polyubiquitylation and turnover of EYA4, it is plausible that tumor-suppressive roles of EYA4 could be blocked by TRIM69." (PMID 36741265, 2023).
tumor (continued). "Although EYA4 may in some cases boost tumorigenic phenotype such as epithelial-mesenchymal transition (EMT) 3, accumulating evidence suggest that EYA4 has crucial tumor-suppressive role in both human and experimental mice malignancies." (PMID 36741265, 2023). "The findings also suggested that EYA4 functioned as a tumor suppressor." (PMID 37156847, 2023). "The expression of EN1 and EYA4 in LGGs was prevalent among some known tumor types." (PMID 35535221, 2022). "To determine whether RAP1 repression is the critical molecular mechanism mediating the tumor-suppressive effects of EYA4 in HCC cells, we co-transfected HCC cells with pEYA4 and Flag-RAP1A." (PMID 29764501, 2018). "Our current study unearthed EYA4 as a novel tumor suppressor that was suppressed in HCC cell lines." (PMID 29764501, 2018). "The in vivo results confirmed the tumor-suppressive effects of the EYA4 gene on ICC cells." (PMID 27469137, 2016). "In vitro, EYA4 overexpression inhibited tumor cell growth, foci formation, and cell invasiveness." (PMID 27469137, 2016). "Thus, TRIM69 impedes tumor-suppressive phenotypes of EYA4 in vivo." (PMID 36741265, 2023). "Besides, EYA4 down‐regulation was significantly associated with tumour differentiation status but not other clinical parameters." (PMID 30957411, 2019). "Hence, our data support the tumour suppressor function of EYA4 in HCC." (PMID 30957411, 2019). "Among the top of the list sorted by the smallest adjusted P values were five genes: ADHFE1, EYA4, FBLIM1, HOXA3, and HOXA5, all hypermethylated in all tumor groups." (PMID 40753397, 2025). "EYA4, a member of the EYA family, has been identified as a promising tumor suppressor in HCC, potentially inhibiting malignant behaviors in HCC cell lines by interfering with NF-κB/RAP1 signaling activation." (PMID 36750914, 2023). "Overexpression of EYA4 suppressed HCC cell migration, invasion and capillary tube formation of endothelial cells in vitro, as well as in vivo tumour angiogenesis and metastasis in a mouse model." (PMID 30957411, 2019). "The expression of EYA4 was obviously increased, while the ID2 expression level was remarkably reduced in tumor tissues of circACVR2A overexpressing group." (PMID 31101108, 2019). "Functional assays showed that forced expression of EYA4 suppressed HCC cell migration, invasion and capillary tube formation of endothelial cells in vitro, as well as in vivo tumour angiogenesis and metastasis in a mouse model." (PMID 30957411, 2019). "Together with the evidence that EYA4 negatively regulated the levels of RAP1 mRNA and protein expression, we further dissected the role of RAP1 in EYA4-mediated tumor suppression by gain-of-function with re-expression of RAP1." (PMID 29764501, 2018). "EYA4 inhibited HCC cell growth, invasion and tumor formation by repression of RAP1, highlighting the important role of RAP1 in EYA4-mediated tumor suppression in HCC development." (PMID 29764501, 2018). "The restoration of EYA4 expression in HCC cell lines suppressed cell proliferation, inhibited clonogenic outgrowth, reduced cell invasion and restrained xenograft tumor growth, and Flag-RAP1A reversed the suppressive effects of pEYA4 in vitro." (PMID 29764501, 2018). "EYA4 gene functioned as a molecular prognostic marker in ICC, and its overexpression inhibited tumor growth in vitro and in vivo." (PMID 27469137, 2016). "EYA4 overexpression suppressed the expression levels of c‐JUN and VEGFA in HCC tumours." (PMID 30957411, 2019). "EYA4, TFPI2 and TLX1 were hypermethylated in more than 90% of all tumours examined." (PMID 28351398, 2017). "Our current study validate TRIM69 as a mutually exclusive E3 ligase targeting EYA4 for polyubiquitylation and turnover, thereby perturbing its ability to deactivate β-catenin/ID2 pathway and suppress cell proliferation, self-renewal as well as tumor development of PDAC cells." (PMID 36741265, 2023). "EYA4 was weakly positive in tumor tissue and negative in normal tissue." (PMID 35535221, 2022).
tumor (continued). "In a previous research, we demonstrated that EYA4 expression is down-regulated in human HCC tissue and that its suppression is an independent prognostic factor of poor survival, which suggests EYA4 might be a potential tumor suppressor gene in HCC." (PMID 29764501, 2018). "Three genes, EYA4, TLX1 and TFPI2 are hypermethylated in >90% of all tumour samples, regardless of CIMP subtype." (PMID 28351398, 2017).
cancer (21 papers, 2009 to 2025). A tumor composed of atypical neoplastic, often pleomorphic cells that invade other tissues. "EYA4 has also been associated with cancer in various organs." (PMID 37292941, 2023). "Further, benzarone caused a dose-dependent elevation in cleaved PARP, indicative of cell death, and phosphorylation of H3 on S10, indicative of mitotic arrest, in cancer cell lines with high expression levels of EYA4 (HeLa), EYA1 (SKNAS), or both (SKNFI)." (PMID 38360978, 2024). "To begin, we explored the dysregulated transcriptional levels of the EYAs (EYA1, EYA2, EYA3, EYA4) family in 34 types of human common cancer." (PMID 37156847, 2023). "We observe that TRIM69 evokes, through degrading EYA4, nuclear β-catenin accumulation and transcription of Id2 gene, which had been reported to favor cancer progression via fostering mitosis, stem cell self-renewal and angiogenesis." (PMID 36741265, 2023). "In this study, we sought to gain a better understanding of the cellular processes impacted by EYA4 deregulation in cancer, and specifically understand the possible role of EYA4 in breast carcinogenesis." (PMID 37292941, 2023). "We assessed the effects of EYA4 deregulation on primary cancer growth and metastasis in vivo using luciferase-expressing cell lines." (PMID 37292941, 2023). "There was significant increase for the positive rates of hTERT or EYA4 mRNA expression in peripheral blood mononuclear cells with the progressive stages from normal cells to cancer in the esophageal carcinogenesis." (PMID 19939248, 2009). "Therefore, in this study, we sought to gain a better understanding of the cellular processes impacted by EYA4 over-expression in cancer, and specifically understand the possible role of EYA4 in promoting and sustaining carcinogenesis of the breast." (PMID 37777742, 2023). "Epigenetic inactivation of tumor suppressor genes EYA4 and GAS1 are associated with progression of various cancer types, but silencing of these genes might associate with progression of pituitary prolactinoma." (PMID 33709028, 2021). "Serum methylated SST was significantly associated with cancer-specific survival among all other detected markers tested in the same study (TAC1, MAL, SEPT9, NELL1, CRABP1, EYA4, and CEA) at the preoperative time point, while its methylation status after operation had no value on prognosis." (PMID 30944663, 2019). "Taken together, our data indicate that EYA4 deficiency in HCC pathogenesis was associated with the hyperactivated NF-κB signaling pathway and up-regulated RAP1 expression, which further contributed to the aggressiveness of malignant liver tumors." (PMID 29764501, 2018). "Over-expression of EYA4 in cancer could be used to predict patient outcomes and drug response." (PMID 37777742, 2023). "Over-expressing EYA4 in cancer could be used to predict patient outcomes and drug response." (PMID 37292941, 2023). "EYA transcription coactivator and phosphatase 4 (EYA4) interacted with PI3K/AKT, Wnt/GSK-3β and various signal proteins of cell cycle pathway, and played its role in promoting or inhibiting cancer." (PMID 39170242, 2024). "Given the aberrant accumulation of proteasome in cancer cells, we were interested in whether ubiquitin-proteasome system (UPS) can manipulate EYA4 protein turnover." (PMID 36741265, 2023). "This analysis also revealed a number of epigenetic oncogenes (KDM1A, HDAC1, TDG) and tumor suppressors (KAT2B, PRDM5, DUSP1, EYA4) which did not correlate significantly with any of the others, suggesting that these may affect cancer DNAm patterns independently of each other." (PMID 26169266, 2015).
gastrointestinal tumors (1 paper, 2010). "Of the top 10 genes that were hypermethylated in CIMP-H compared to CIMP-L tumors, 5 have previously been implicated in the pathogenesis of gastrointestinal tumors (NTRK3, HS3ST2, TWIST1, CD40 and EYA4)." (PMID 20492682, 2010).
lung (1 paper, 2017). "In summary, our results showed that the promotor regions of HOXA11, CDKN2A EX2 and EYA4 were frequently methylated in human lung AD tissues." (PMID 28380439, 2017).
EYA4 also shares sentences with these, for which no sentence is quoted: Hearing impairment (4 papers); malignant peripheral nerve sheath tumor (4); Barrett esophagus (2); breast tumor (2); gastric cancer (2); intrahepatic cholangiocarcinoma (2); acute myeloid leukemia (1); adenocarcinoma (1); age (1); deafness autosomal recessive 28 (1); esophageal diseases (1); heart disease (1); heart failure (1); nervous system cancer (1); nervous system tumors (1); nonsyndromic deafness (1); Obesity (1); Onset (1); otofaciocervical syndrome (1); primitive neuroectodermal tumor (1); sensorineural hearing loss (1); tubular adenoma (1); Wilms tumor (1).